INS (insulin)
Diseases named in the same sentence as INS in open-access papers (continued):
Sharing a sentence is not in itself a finding about the gene and the disease.
diabetes (continued). "There was no significant change on questions 3 and 5 (ILO’s: managing patients on IV insulin and managing hypoglycaemia) and a decrease in score on question 9 (ILO: altering diabetes therapy prior to procedures)." (PMID 26956764, 2016). "The results support the concept that fuel excess can drive obesity and diabetes via hyperinsulinaemia, and that an islet beta cell ATGL-lipolysis/adipose tissue axis controls energy homeostasis and body weight via insulin secretion." (PMID 27677764, 2016). "Also, recent studies suggested that dietary intake of Omega-3 could be useful in prevention of diabetes; as it reduced the activity of the pro-inflammatory processes which stimulated the body to attack its own insulin-producing cells; hence it was used in this study." (PMID 26894845, 2016). "Several clinical studies have reported the safety and efficacy of SGLT2 inhibitors in combination with insulin in patients with T1DM, however diabetic ketoacidosis has been reported in some studies." (PMID 27316668, 2016). "One of these studies enrolled 89 patients with diabetes and a renal clearance of 34.1±11.5 mL/min who were treated with oral antidiabetic drugs or NPH insulin, although with sub-optimal glycemic control or frequent hypoglycemic episodes." (PMID 26872083, 2016). "Islet morphology, insulin secretion, glucose tolerance, and multiple low-dose streptozotocin (STZ)-induced diabetes incidence were evaluated and compared between HDAC3 knockout and wild type littermate controls." (PMID 27542279, 2016). "Few examples include PPARG mutation in familial partial lipodystrophy (FPLD3), INSR in Donahue syndrome and Type A insulin resistance, HNF4A in Maturity-Onset Diabetes of Young (MODY1), and INS in Diabetes-type hyperglycemia and hyperinsulinemia." (PMID 27376154, 2016). "Duration of diabetes, A1C levels, SBP, heart rate, CVD, and insulin treatment all displayed a direct relationship with DR." (PMID 26886129, 2016). "Diabetes was induced with the use of streptozotocin (56.3% of the studies), PEG300 (6.25%), and insulin solution (12.5%)." (PMID 27843476, 2016). "Diabetes mellitus (DM) is a metabolic disease with decreased glucose transport into muscle and fat cells and increased hepatic glucose output resulting from dysfunction in insulin secretion or resistance to its activity." (PMID 27418937, 2016). "Physicians thought that registered nurses interpreted diabetes symptoms appropriately, but found that they deviated from their set orders for CBGM and insulin injections due to concerns about potential hypoglycaemia." (PMID 26855612, 2016). "Maladies of diabetes cannot be totally corrected by insulin treatment; previous work suggested that antioxidant therapy may be an important adjunct treatment regimen for DM." (PMID 27164129, 2016). "Fasting glucose, insulin and HOMA levels and prevalence of diabetes and metabolic syndrome showed significant differences between birth weight categories in women but not in men." (PMID 27141948, 2016). "Given the worse regulation of diabetes in insulin users (Hba1c in PAD-IDDM 78 mmol/mol versus 49 mmol/mol in PAD-NIDDM), we cannot discriminate the role of exogenous insulin use versus worse diabetic control." (PMID 27887576, 2016). "Baseline knowledge was lowest in managing patients on IV insulin, diagnosing and managing HHS, managing patients on oral hypoglycaemic agents and altering diabetes therapy prior to surgery." (PMID 26956764, 2016). "Palmitic acid (16:0) has been correlated with decreased insulin sensitivity whereas, stearic acid (18:0) may have a protective effect against cardiovascular disease, and very-long-chain SFA (>22 carbon atoms) have been associated with a lower risk for diabetes." (PMID 26930646, 2016). "Oral administration of RJ improves the serum levels of AST, ALT, ALP, TP, HDL-c, insulin, FBG and albumin in STZ-induced diabetes." (PMID 27602318, 2016).
diabetes (continued). "In muscle, insulin signaling via IRS and PI3K is attenuated, whereas the stimulation of the MAPK pathway by insulin is thought to be intact in hyperinsulinemia and type 2 diabetes mellitus (T2DM)." (PMID 27247938, 2016). "Additionally, similar to what has been reported, we found that irisin is positively associated with insulin sensitivity (HOMA2-%S), even after controlling multiple covariates such as age, gender, BMI, blood lipids, antidiabetic medications, and the duration of diabetes." (PMID 26649318, 2016). "Average diabetes years of using OAD group was 2.18 years and average diabetes years of using insulin group was 8.13 years." (PMID 27904812, 2016). "Type 2 diabetes mellitus (T2DM) results from a combination of insulin resistance and impaired insulin secretion, where insulin resistance has been described as the most important pathophysiological feature in prediabetic states." (PMID 27562101, 2016). "Surprisingly, instead of the diabetes-like elevation seen in HFD males, serum insulin concentrations were significantly reduced in HFD-fed females compared to CD females (p = 0.005)." (PMID 26823968, 2016). "Data were used from the Initiative for Quality improvement and Epidemiology in patients with Diabetes (IQED), a nationwide quality improvement initiative among insulin-treated diabetic patients attending hospital-based specialist diabetes centres in Belgium." (PMID 27553193, 2016). "This post hoc analysis examined the efficacy and safety of twice-daily insulin lispro low mixture (LM25) and once-daily basal insulin glargine plus once-daily prandial insulin lispro (IGL) in a Latin American subpopulation with type 2 diabetes mellitus (T2DM)." (PMID 27660663, 2016). "Here we report that the novel IL-1βR antagonist SER140 is able to postpone the onset of diabetes in female NOD mice coupled to an overall decrease in BG levels and increased insulin levels upon treatment." (PMID 26953152, 2016). "Additionally, the increased risk of progression to diabetes seen with high-intensity statin treatment might also occur with PCSK9 inhibition, possibly resulting from the intracellular accumulation of lipids in insulin-secreting pancreatic beta cells." (PMID 27095708, 2016). "It is thus interesting to explore how the Insulin/PI3K/Akt pathway is fine-tuned and how they go awry in the context of diabetes." (PMID 26908121, 2016). "By using the cell culture model, we explored the mechanism how Inpp5f regulates the Insulin/PI3K/PKB/Akt pathway and thus glucose uptake in the context of diabetes." (PMID 26908121, 2016). "The proportions with diabetes and overweight/obesity, the lipid profiles (TG, LDL-C, TG/HDL-C, TC/HDL-C, LDL-C/HDL-C), fasting and postprandial plasma glucose, insulin, and C peptide were much higher in the HOMA-IR >2.69 group." (PMID 27267043, 2016). "TG and SG had a similar duration of diabetes (DOD), HbA1c, baseline insulin dose, lipid profile and creatinine." (PMID 27561827, 2016). "In patients with mental disorder, NEAT score showed an inverse correlation with duration of diabetes (r = −0.339, P = 0.016), and there was a tendency toward a significant correlation between NEAT score and serum insulin (r = −0.32, P = 0.05)." (PMID 26765475, 2016). "Systemic or hepatic blockage of RANKL signaling in mice significantly improves hepatic insulin sensitivity and promotes normalization of BGL in type 2 diabetes mellitus mouse models." (PMID 26751951, 2016). "Only in diabetes subjects did they observe a significant increase in serum FGF23 levels after clamp, which was correlated with the increase in insulin levels." (PMID 27698482, 2016). "The main pathophysiological defects responsible for type 2 diabetes mellitus (T2DM) are β cell dysfunction and decreased insulin sensitivity." (PMID 26640807, 2016).
diabetes (continued). "Loss of PICK1 and ICA69 leads to impaired conversion of proinsulin to mature insulin, and PICK1 KO mice display diabetes-like symptoms such as glucose intolerance, insufficient insulin release, and elevated proinsulin secretion." (PMID 26868290, 2016). "Subjects receiving insulin and those who had carried a diagnosis of diabetes for a longer period of time had greater prevalence of CAD, and insulin use was the most specific single clinical characteristic for the presence of coronary disease." (PMID 26861208, 2016). "Diabetes was induced in mice by employing streptozotocin(STZ), a chemical that is toxic to insulin-producing β cells of the pancreas." (PMID 27553852, 2016). "Although the association between diabetes/retinal cell apoptosis and the onset time of diabetic retinal neurodegeneration has been well documented, less is known about whether RGC loss also occurs in the period of insulin resistance (in other words, prior to the development of diabetes)." (PMID 28050322, 2016). "Annually collected data on diabetes medication and clinical variables within ZODIAC are used to evaluate the primary outcome, time to insulin and secondary outcome, time to either insulin or triple oral therapy." (PMID 27327605, 2016). "Elucidating the regulation of glucose-stimulated insulin secretion (GSIS) in pancreatic β cells is important for understanding and treating diabetes." (PMID 26986842, 2016). "Different mechanisms have been proposed to explain the possible influences of diabetes on bone metabolism, including glycosuria, AGEs, low levels of IGF-I or alteration in plasma insulin levels, impaired kidney function, and chronic inflammation." (PMID 28044077, 2016). "Interestingly, C-peptide was measurable at diabetes onset (1.04 ng/ml or 0.35 nmol/l), but became undetectable in patient 2 (CSII only) after 12 and 24 months from diabetes diagnosis, consistent with other reports showing this pattern in patients with INS proteotoxic mutations." (PMID 26239141, 2016). "Microarrays were used to assess miRNA expression in skeletal muscle biopsies taken from healthy individuals and patients with pre-diabetes or T2DM, and insulin resistant offspring of rat dams fed a high fat diet during pregnancy." (PMID 27163678, 2016). "Diminished glucose oxidation rates in cardiomyocytes occur as early as 48 h after the induction of diabetes by STZ treatment, which is reversed by insulin treatment." (PMID 27014078, 2016). "CDC reported that approximately 81% of diagnosed diabetes (including type 1 and T2DM) patients aged 18 and above in 2011 were treated with either oral drugs, insulin, or both based on self-reported data, while we found that 77% (T2DM only) receive medication." (PMID 27895533, 2016). "Women with low birth weight (≤2.5 kg) had higher levels of fasting plasma glucose, insulin, HOMA, diabetes and metabolic syndrome; a non significant similar trend was seen in men." (PMID 27141948, 2016). "An altered response to a GTT can serve as an indicator of diabetes mellitus type 2 (DM2), which is characterized by an inability to effectively and efficiently transfer glucose from the bloodstream into tissues via insulin signaling." (PMID 27482817, 2016). "Out of 129 insulin-treated people with diabetes identified by USS as having LH lesions, only 40 agreed to participate in the study (24 females, age 54 ± 15 years, daily insulin dosage 57 ± 12 IU)." (PMID 27213130, 2016). "Maintaining relatively low levels of fasting insulin and HOMA-IR is shown to be beneficial for the prevention and treatment of diabetes." (PMID 27763537, 2016). "The main pathophysiological defects responsible for type 2 diabetes mellitus (T2DM) include β cell dysfunction and decreased insulin sensitivity." (PMID 26640807, 2016).
diabetes (continued). "Compared with the survival patients, the deceased patients were more likely to be male and older, had a longer duration of diabetes, lower mean of BMI, higher mean of SBP, higher mean FPG and CV of FPG, and more frequently used insulin." (PMID 28004765, 2016). "In type 1 diabetes mellitus (T1DM) animals, dietary supplementation of genistein led to modulation of glucose metabolism and insulin levels." (PMID 27092490, 2016). "On the other hand, the plasma adiponectin levels were positively correlated with age, diabetes duration, systolic BP, serum creatinine, and HDL-cholesterol and negatively correlated with BMI, eGFR, immunoreactive insulin, HOMA-R, and serum triglyceride levels." (PMID 28070523, 2016). "We performed oral glucose tolerance test (OGTT) and plasma GLP-1 and insulin secretion by multiplex assays to investigate antidiabetic effects of LJT, RGL, and JAL2 in db/db mice, the mice model of type 2 diabetes mellitus (T2DM)." (PMID 27069493, 2016). "Combination treatments with insulin and other chemical compounds produce beneficial effects on STZ-induced diabetes and DCM." (PMID 28078246, 2016). "There is evidence that insulin-dependent diabetic patients with CAD present with increased levels of cytokines independently of glycemic control, the duration of diabetes, and the extent of CAD." (PMID 27597799, 2016). "In summary, we demonstrated that the use of an insulin sensitizer, in this case OFS, in conjunction with an immune modulatory therapy (i.e. aCD3), is a viable paradigm to induce diabetes remission in early established diabetes." (PMID 27874076, 2016). "Central insulin administration in STZ treated rats induce normal LH surge, despite the maintenance of peripheral diabetes revealing that insulin action on reproduction occurs at multiple levels." (PMID 26875986, 2016). "We demonstrate that humoral and cellular immune responses against insulin were detected in a subset of diabetic dogs treated with exogenous insulin, suggesting that approaches to induce antigen-specific tolerance could be an option to improve glycemic control of dogs with diabetes." (PMID 27031512, 2016). "Women with insulin-treated gestational diabetes mellitus (GDM) require close monitoring and support to manage their diabetes." (PMID 27507708, 2016). "Induction of diabetes using STZ in rodents results in the destruction and necrosis of the beta cells of the pancreas which consequently leads to diminished insulin release and elevated blood glucose levels." (PMID 27403200, 2016). "Traits with significant correlation within the glucose homeostasis group were M value, IGI30, insulin at 120 minutes of the OGTT, HOMA-%B, and diabetes status, the latter two of which also remained significant in multivariate analysis in this domain." (PMID 27846285, 2016). "Accordingly, the increase in glucose of diabetics leads to high DPPIV-ADA and increase in DPPIV-ADA results in incretin reduction and insulin secretion." (PMID 28050278, 2016). "These newly generated β cells increased the serum insulin levels and ameliorated STZ-induced diabetes." (PMID 27526291, 2016). "We used an established model of diabetes induction in vivo, by a single injection of streptozotocin (STZ), a toxic chemical, preferentially transported to and directed against insulin producing, pancreatic beta cells from islets of Langerhans." (PMID 27803936, 2016). "In the subgroup of patients with diabetes, the data showed that the differential of HDL-C in the ICO group was less than that in the GLU group (P = 0.002) and insulin levels in the ICO group were lower than those in the GLU group (P = 0.01)." (PMID 26788499, 2015). "In conclustion, GB extract feeding inhibits the decrease of expression of FOXO1 and PPARγ, and increases insulin signaling, contributing to the improvement of insulin sensitivity in aged mice.Therefore, GB extract might have a potential to ameliorate age-related metabolic disorder such as diabetes." (PMID 25912041, 2015).
diabetes (continued). "MT-tg overexpression significantly protected mice from acute STZ-induced ROS at 8 weeks of age; unexpectedly, however, MT-tg impaired glucose stimulated insulin secretion (GSIS) and promoted the development of diabetes." (PMID 26335571, 2015). "Failure of insulin to appropriately suppress EGP, i.e., hepatic insulin resistance, is an important contributor to the development of hyperglycemia and (pre)diabetes." (PMID 26635731, 2015). "Evidence of enhanced insulin signaling following long term rapa, and intermittent rapa, as well as little evidence for detrimental mitochondrial function following rapamycin, supports the hypothesis that rapamycin may in fact be inducing changes similar to starvation diabetes." (PMID 26568298, 2015). "We focused on certain parameters that can directly or indirectly reflect the insulin secretory function, such as PCGR, duration of diabetes, and medication history of DPP-IV inhibitor which can effectively reduce postprandial glucose." (PMID 26484352, 2015). "Initially, this convention targeted only type 1 diabetes mellitus (T1DM) and later on, the target public also included the growing number of patients with T2DM with at least 2 insulin injections a day." (PMID 26171143, 2015). "Insulin therapy in Type 2 Diabetes Mellitus (DM) is normally indicated either when oral hypoglycemic medications do not seem to be effective (uncontrolled blood glucose levels despite the use of oral hypoglycemic agents) or initiated especially when these patients suffer from diabetic complications." (PMID 26446829, 2015). "These were characterised by immunostaining, patch-clamp electrophysiology, insulin secretion, transcriptome analysis and transplantation into a streptozotocin (STZ)-induced mouse model of diabetes." (PMID 25930156, 2015). "Even increments in serum glucose and insulin levels were observed after 8-weeks EGCG-rich green tea extract intervention, leading to the development of diseases such as diabetes." (PMID 26264374, 2015). "GLP-1 enhances insulin secretion and inhibits glucagon release in a glucose-dependent manner, prompting the development of GLP-1-based therapies for the treatment of diabetes." (PMID 25785276, 2015). "Diabetes implications: Amylin/leptin use has also been connected with beneficial influences on glycaemic markers such as FBG, insulin and HOMA-IR." (PMID 25894803, 2015). "GLP-1-based diabetes therapies affect glucose control through several mechanisms, including slowed gastric emptying, regulation of postprandial glucagon, reduction of food intake, and enhancement of glucose-dependent insulin secretion without the risk of hypoglycemia." (PMID 25785276, 2015). "Type 1 diabetes mellitus (T1DM) is an autoimmune disease wherein an improper autoimmune response affects and destroys insulin-producing β-cells in pancreatic islets, which leads to impaired blood glucose levels." (PMID 25726699, 2015). "Medical comorbidities (e.g., smoking, diabetes, vascular insufficiency, osteoporosis, cancer, and rheumatoid arthritis), and use of medications (e.g., prescription NSAIDs, anticoagulants, steroids, antibiotics, insulin, and calcium channel blockers) may increase the risk of nonunion in the elderly." (PMID 25886761, 2015). "Reprogramming acinar cells into insulin producing cells using adenoviral (Ad)-mediated delivery of Pdx1, Ngn3 and MafA (PNM) is an innovative approach for the treatment of diabetes." (PMID 26690959, 2015). "In summary, hypoglycemia in insulin-treated patients with diabetes might result from various causes, among which immunological causes associated with IAbs shall not be neglected, although it is a rare etiology and insulin overdose should always be addressed before considering other causes." (PMID 25961056, 2015). "Median duration of diabetes at index date was 1 year in all groups, with proportions of patients with DD above 5 years in insulin, EBID and EBID + insulin groups at 6%, 8% and 11% respectively." (PMID 25616979, 2015).